STAT3 (signal transducer and activator of transcription 3)
Diseases named in the same sentence as STAT3 in open-access papers (continued):
Sharing a sentence is not in itself a finding about the gene and the disease.
lung carcinoma (continued). "Given the important role of abnormally activated STAT3 in the occurrence and progression of lung cancer, targeted inhibition of STAT3 may become an effective therapeutic strategy for lung cancer." (PMID 36559280, 2022). "STAT3 phosphorylation regulates cancer metastasis and may be used as a biomarker of poor prognosis in lung cancer." (PMID 35586682, 2022). "Recent studies have shown that microRNAs could promote proliferation, migration, invasion, anti-apoptosis, and angiogenesis of lung cancer cells by activating STAT3." (PMID 36559280, 2022). "Another study also showed that PD-L1 expression may be enhanced by CKS1B/STAT3 axis, further promoting lung cancer development." (PMID 36405738, 2022). "Our results showed that rhein plays a vital role in proliferation and metastasis of chemosensitive and chemoresistant lung cancer cells, and the mechanism may be related to the Stat3/Snail/MMP2/MMP9 pathway." (PMID 35178453, 2022). "Furthermore, immunostaining of clinical samples from the SHTCH lung cancer cohort also revealed a strong positive correlation between IL-20RB expression and STAT3 phosphorylation." (PMID 36006737, 2022). "In this study, we hypothesized that TGF-β1/SH2B3 axis participated in lung cancer development by modulating JAK2/STAT3 and SHP2/Grb2 signaling pathways." (PMID 35589677, 2022). "AKIRIN2 is necessary for the growth and metastasis of lung cancer and liver cancer and promotes the angiogenesis of gallbladder cancer through interleukin-6 (IL-6)/signal transducer and activator of transcription 3 (STAT3)/vascular endothelial growth factor A (VEGFA)." (PMID 36059811, 2022). "Previous studies demonstrated that overexpression of TRIM32 could promote proliferation of lung cancer cells by activating JAK2/STAT3 signaling pathway." (PMID 35756612, 2022). "The IL-6/STAT3 pathway is hyperactivated in patients with many cancer types, including lung cancer." (PMID 36547079, 2022). "After transfecting the human IL-22 cDNA into lung cancer A549 and PG cells, the overexpression of IL-22 inhibited the chemotherapy-mediated apoptosis of A549 and PG cells through the activation of STAT3 and its downstream antiapoptotic proteins, such as Bcl-2 and Bcl-xl." (PMID 35669104, 2022). "GWAS have shown that α5-nAChR is highly associated with lung cancer risk and nicotine dependence.Our previous study reported that α5-nAChR mediates nicotine-induced LUAD development and progression via the PI3K and JAK2/STAT3 pathways." (PMID 35971127, 2022). "Moreover, silencing circHIPK3 results in the reduction of cell proliferation, migration invasion, and promotion of macroautophagy/autophagy via MIR124-3p-STAT3-PRKAA/AMPKα signaling in STK11 mutant lung cancer." (PMID 36338714, 2022). "In addition, STAT3 partially coordinates the cisplatin-resistance phenotype in non–small-cell lung cancer, providing support for the combination of cisplatin, rapamycin, and STAT3 abrogation as a rational therapeutic approach for lung cancer." (PMID 36509291, 2022). "To investigate the molecular mechanisms underlying the function of the TGF-β1/SH2B3 axis in lung cancer, we next determined whether and how TGF-β1 modulated JAK2/STAT3 and SHP2/Grb2/PI3K/AKT signaling." (PMID 35589677, 2022). "The IL-6/STAT3 pathway plays an important role in tumor metastasis, including lung cancer." (PMID 36547079, 2022). "Taken together, these data indicated that combination with IFNγ and STAT3 inhibitor could inhibit the proliferation of lung cancer cells by promoting apoptosis and cell cycle transition." (PMID 36185620, 2022). "MiR-22-3p suppressed cell growth via MET/STAT3 signaling in lung cancer." (PMID 36276078, 2022). "The exosome-mediated transfer of miR-193a-3p, miR-210-3p, and miR-5100 could also enhance lung cancer cell metastasis by activating STAT3 signaling-induced EMT." (PMID 36233088, 2022).
lung carcinoma (continued). "It has been reported that LINC01116 is overexpressed in lung cancer and that it could upregulate STAT3 to induce tumor invasion and migration." (PMID 35372012, 2022). "Previous studies have found that the abnormal activation of STAT3 in the development of KRAS mutant lung cancer, which will be attenuated under anti-IL-6 therapy, suggesting a tight association between IL-6/STAT3 signaling and inflammation in KRAS-activated tumorigenesis." (PMID 36619616, 2022). "Another study indicated that STAT3 might prevent the initiation of lung cancer by maintaining pulmonary homeostasis under oncogenic stress, but it may also facilitate the progression of lung cancer by promoting the growth of cancer cells at the same time." (PMID 36559280, 2022). "Therefore, inactivating STAT3 via STAT3 inhibitors is a significant approach to devastate the resistance of paclitaxel in lung cancer." (PMID 35281907, 2022). "Furthermore, STAT3 inactivation incapacitates paclitaxel resistance in several carcinomas as well as lung cancer in either independent or synergistic manner." (PMID 35281907, 2022). "In addition, we also introduce the potential application of NPs-based targeted delivery of STAT3 inhibitors in the treatment of cancers, including lung cancer." (PMID 36559280, 2022). "Nevertheless, whether JAK2/STAT3 signaling regulates anoikis resistance in lung cancer remains unknown." (PMID 35589677, 2022). "Our results indicate that inhibition of the adaptive survival via STAT3 combined with an ALK-TKI may improve the outcomes of ALK-rearranged lung cancer." (PMID 35228642, 2022). "In order to investigate how GYP exerts its anti-LC effects by regulating metabolites and metabolic pathways as well as enhancing the anti-lung cancer effects of chemotherapeutic agents, the relative contents of STAT3, EGFR, MAPK14, and TYMS between the six groups were analyzed by western blot." (PMID 36532716, 2022). "HB-EGF cleavage by matrix metalloproteinase 14 may enhance the EGFR signaling pathway to increase cancer cell growth in NSCLC and promotes lung cancer cell proliferation through the signal transducer and activator of transcription 3 (STAT3) signaling pathway." (PMID 36439487, 2022). "Thus, we further propose a novel Stat3 dependent targetable mechanism that is instrumental in mediating the migration and invasion of lung cancer cells." (PMID 36140747, 2022). "Similarly, miR-3127-5p upregulated PD-L1 expression on lung cancer cells by promoting STAT3 phosphorylation, leading to chemoresistance." (PMID 36248881, 2022). "After test the key factors’ activity associated with these pathways by Immunohistochemical (IHC) staining and western blotting, the activation of JNK phosphorylation and inhibition of p38 and STAT3 phosphorylation was observed both in TR35 treated lung cancer cell and tumor tissue." (PMID 34760885, 2021). "The STAT3 signaling pathway may be aberrantly activated and have crucial roles in various tumor, including lung cancer." (PMID 34670194, 2021). "Also, miR-218 served as a tumor suppressor in lung cancer by affecting the interleukin-6/STAT3 axis." (PMID 33896365, 2021). "JNK activation and STAT3 inhibition are reported to induce M1 macrophage polarization in lung cancer, which may have anti-tumor effects." (PMID 34760885, 2021). "Interestingly, both curcumin and metformin, an anti-diabetic drug, were found to inhibit EMT by blocking the IL-6/STAT3 axis–curcumin in hepatocellular carcinoma and metformin in lung cancer." (PMID 34944855, 2021). "Moreover, it was also found that hsa-miR-320a-3p, by inhibiting the expression of both STAT3 and phosphorylated p-STAT3 (p-STAT3), further induced lung cancer cell apoptosis." (PMID 34071109, 2021). "The aberrant activation of STAT3 is correlated to poor clinical outcomes of lung cancer." (PMID 34321456, 2021). "Lung cancer with constitutively activated STAT3 is one of the most malignant cancers." (PMID 33391507, 2021).
lung carcinoma (continued). "AKR1C1 can activate STAT3, thereby promoting lung cancer metastasis." (PMID 33928101, 2021). "A panel of miRNAs, miR-193a-3p, miR-210-3p, and miR-5100, in hypoxic bone-marrow stem-cell-derived exosome promotes lung cancer metastasis via STAT-3 induced EMT, which may be a candidate biomarker for cancer metastasis." (PMID 34660694, 2021). "In addition, lncRNA ATB activated AKT and the JAK/STAT3 signaling pathway through down-regulated miR-494 in lung cancer." (PMID 33658048, 2021). "These evidences suggested that targeting STAT3 may provide a new strategy to overcome EGFR-TKI acquired resistance in lung cancer." (PMID 33391507, 2021). "Meanwhile resveratrol has been proved to inhibit STAT3 activity in lung cancer." (PMID 34633989, 2021). "Tegaserod maleate has been shown to exert anticancer activity by inducing apoptosis in melanoma cells, and it has been identified as a JAK/STAT3 signal inhibitor, impeding the growth of a variety of cancer cells, including lung cancer, prostate cancer, colon cancer, and cervical cancer." (PMID 34422635, 2021). "TRIM32 overexpression promotes lung cancer cell proliferation by activating the JAK2/STAT3-signaling pathway, as STAT3 has also been implied in muscle wasting during cancer, it would be interesting to test if TRIM32 also activates this inflammatory pathway in muscles." (PMID 33802079, 2021). "Likewise, tumor cell-extrinsic activation of STAT3 in immune cells such as B-cells and MDSCs enhances angiogenesis and the growth of lung cancer allografts in mice." (PMID 34944848, 2021). "The results indicated that miR-526b-3p inhibited STAT3 in cisplatin-resistant lung cancer." (PMID 34321456, 2021). "Taken together, in the present study we demonstrated that W2014-S, as a novel STAT3 inhibitor, effectively inhibited STAT3 signaling with potent anti-tumor activities in human lung cancer, and enhanced the sensitivity of resistant NSCLC to gefitinib in vitro and in vivo." (PMID 33391507, 2021). "Interestingly, blockade of the AT1-R with losartan inhibited the expression of phospho(Tyr705)-STAT3 in lung cancer cells, suggesting that STAT3 activation is, at least in part, dependent upon activation of the AT1-R." (PMID 33380422, 2021). "Inhibiting STAT3 phosphorylation attenuates malignant progression in lung cancer cells." (PMID 34059057, 2021). "In addition, SOCS3, A20 (TNFIAP3), and CYLD, the transcriptional targets of STAT3 and RelA, were increased in the lung macrophages of mice with lung cancers." (PMID 33539325, 2021). "Abnormal activation of STAT3 promotes cells proliferation and invasion in lung cancer." (PMID 34059647, 2021). "Further, miR-526b-3, miR29b-3p and miR93-3p elevated in Tibetan placentas could target STAT3, as reported in lung cancer, liver fibrosis, and renal cell carcinoma." (PMID 34567059, 2021). "Besides, (-)-Guaiol, which is an effective constituent of the Fuzheng Quxie Formula, inhibited the EMT process of lung cancer by targeting M2 macrophages, and IL-10/STAT3 pathway is involved in the regulation of signaling pathway." (PMID 34475962, 2021). "Besides, other factors activated by EGFR such as the EGFR downstream STAT3 has also been demonstrated contributing to radioresistance as a therapeutic target reverses radioresistance in lung cancer." (PMID 34685495, 2021). "Another study also showed GKS1B/STAT3 axis could enhance the expression of PD‐L1 and further promote cancer development of lung cancer cells." (PMID 32960462, 2021). "For example, miR-608 attenuated lung cancer malignancy in a JANK2/STAT3 dependent manner." (PMID 34321456, 2021). "In STK11 mutant lung cancer cell lines (A549 and H838), the miR124-3p-STAT3-PRKAA/AMPKa axis had been reported, which could regulate circHIPK3-induced cell autophagy." (PMID 33681194, 2021). "Inactivation of STAT3 can overcome drug resistance in lung cancer." (PMID 34129726, 2021). "JAK/STAT3 signaling was also found to be required for TGF-β-induced EMT in lung cancer cells." (PMID 34884812, 2021).
lung carcinoma (continued). "We manipulated the expression of STAT3 in A549/GR and PC-9/GR cell lines by siRNA and plasmid, and we found that STAT3 regulates the cell biological function in gefitinib resisitance lung cancer cells." (PMID 34059647, 2021). "According to their results, in some tumors (melanoma, glioma, pancreatic, and lung cancer cells) PKCε could induce phosphorylation of S727 residue leading to an increase in STAT3 transcriptional activity." (PMID 34440160, 2021). "This ability of CSCs is commonly found in ovarian, glioblastoma, liver, breast and lung cancers through activating the signal transducer and activator of transcription 3 (STAT3) and nuclear factor-κB (NF-κB) pathways and cytokines such as interleukin (IL)-8 and IL-10." (PMID 34235155, 2021). "In addition, we further confirmed in clinical samples that the expression of p-STAT3 is elevated in gefitinib-resistant lung cancer tissues." (PMID 34059647, 2021). "As a direct target of WFDC21P, STAT3 phosphorylation was increased in lung carcinoma cells." (PMID 34301920, 2021). "Also, TCM decoction was found to markedly inhibit the EMT of lung cancer cells by downregulating the activator of STAT3 and mesenchymal markers such as N-cadherin and vimentin." (PMID 34867344, 2021). "Recent studies found CKS1B could regulate STAT3 and further influence cancer development of lung cancer and myeloma." (PMID 32960462, 2021). "DDIAS or STAT3 overexpression restored lung cancer cell growth in the presence of DGG-100629." (PMID 33859351, 2021). "In addition, resveratrol inhibits the growth of lung cancer by inhibiting the M2-like polarization of TAMs and inhibiting the activation of STAT3 in tumor cells." (PMID 33224886, 2020). "To address this issue, we initially evaluated whether STAT3 was constitutively activated by nicotine in lung cancer cells." (PMID 31956373, 2020). "The newly identified mechanism suggests that targeting the STAT3 pathway might improve treatment results in some human lung cancer with high levels of Mcl-1." (PMID 31956373, 2020). "Hence, the protein expression of STAT3 in colorectal cancer, renal cancer, and lung cancer revealed lower levels compared with normal tissues, showing a similar result to mRNA transcriptional levels." (PMID 32486001, 2020). "Thus we show that DDIAS prevents PTPRM/STAT3 binding and blocks STAT3 Y705 dephosphorylation, thereby sustaining STAT3 activation in lung cancer." (PMID 31900385, 2020). "Similarly, exosome-mediated transfer of miR-210-3p promotes lung cancer cell invasion by activating STAT3 signaling-induced EMT27." (PMID 32908121, 2020). "To confirm whether the pro-apoptotic effects of KCP10043F are associated with STAT3, we evaluated the apoptotic effects of KCP10043F on STAT3-overexpressed A549 human lung cancer cells with pMXs-STAT3C transfection." (PMID 32150979, 2020). "In A549 human lung carcinoma cells, it inhibited constitutive and IL-6-inducible STAT3 activation." (PMID 32545187, 2020). "Moreover, IHC analysis demonstrated correlation between the DDIAS expression level and STAT3 phosphorylation in lung cancer patient tissues." (PMID 31900385, 2020). "This study revealed for the first time that HHDMNQ induced mitochondria-dependent apoptosis and G2/M cell cycle arrest promoted the accumulation of ROS and mediated MAPK/STAT3/NF-κB signalling pathways and then regulated the downstream-related apoptosis and cycle proteins in A549 lung cancer cells." (PMID 32849902, 2020). "Likewise, the role of oxidative stress in the inhibition of STAT3 activation in lung cancer has already been conferred." (PMID 33013353, 2020). "We confirmed that DDIAS is involved in STAT3 activation in malignant lung cancer." (PMID 31900385, 2020). "In serine/threonine kinase 11 (STK11) mutant lung cancer, circHIPK3 could modulate autography through miR-124-3p-STAT3-PRKAA/AMPKα signaling." (PMID 33163392, 2020). "STAT3 is mainly activated in several cancers including lung cancer." (PMID 32150979, 2020).
lung carcinoma (continued). "Similar effects were observed in a genetically engineered lung cancer mouse model within this study: simultaneous deletion of STAT3 and activation of oncogenic K-RAS in the lung epithelium resulted in increased tumor numbers, but ultimately reduced tumor growth/burden." (PMID 32365499, 2020). "Similarly, hypoxic BM stromal cells-derived exosomal miRNAs promote metastasis of lung cancer cells via STAT3-induced EMT in an in vivo mouse syngeneic tumor model." (PMID 33299638, 2020). "In addition, treating lung cancer cells with the PI3K/Akt inhibitor LY294002 or the JAK/STAT3 inhibitor AG490 blocked TAM-induced cell migration." (PMID 32283687, 2020). "Mechanistically, H19 acts as a sponger of miR-19 to enhance STAT3 expression in lung cancer and it may also target miR-107, miR-21, miR-196b and miR-484 in different types of lung cancers." (PMID 32272875, 2020). "Additionally, the treatment of lung carcinoma cells with cucurbitacin I inhibited IL-6 induced STAT3/JAK2 signalling." (PMID 32731620, 2020). "Several studies have reported that let-7a could inhibit the growth of cells in lung cancer and lymphoma and STAT3 signalling was influenced by miR-let-7a in cervical carcinogenesis.." (PMID 32208417, 2020). "Furthermore, we confirmed that overexpressing p65 elevated IL6 expression, and subsequent STAT3 activation resulting in enhanced lung cancer cell growth rate." (PMID 32963220, 2020). "Similarly, some studies have shown that activation of STAT3/Bcl-2/caspase 3 signaling can promote apoptosis of NSCLC cells, and acquired resistance of EGFR-mutated lung cancer to TKI treatment is related to the anti-apoptosis effect of the PARP pathway." (PMID 32778129, 2020). "Then we examined the correlation between DDIAS and STAT3 activation in several lung cancer cells." (PMID 31900385, 2020). "Our study illustrated that microRNA-608 may restrain the abilities of proliferation, migration, and invasion of lung cancer cells by targeting BRD4 through the JAK2/STAT3 pathway." (PMID 31621555, 2020). "Furthermore, using an inhibitor of JAK2, which is upstream of STAT3, affected survivin expression and sensitized lung cancer to radiation in vitro and in vivo." (PMID 32872659, 2020). "Furthermore, NF-κB and STAT3 are constitutively activated in lung cancer and are promising targets for the development of novel cancer drugs." (PMID 32849902, 2020). "Therefore, we examined the STAT3 cascade in nicotine regulation of Mcl-1 transcription in human lung cancer cells." (PMID 31956373, 2020). "The present study was performed to determine whether Mcl-1 was mediated by STAT3 signal pathway induced by nicotine in human lung cancer cells." (PMID 31956373, 2020). "Therefore, we suggest that DDIAS can serve as a biomarker to predict the STAT3 phosphorylation in malignant lung cancer." (PMID 31900385, 2020). "In this study, we used human lung cancer cells to investigate the non-canonical functions of STAT3, which has been implicated in many human cancers and has been reported to also have tumor suppressor function." (PMID 32087696, 2020). "Sun et al45 found that a low level of KLF3 is associated with the poor prognosis of lung cancer, and KLF3 could alter the epithelial‐mesenchymal transition by controlling STAT3, ultimately affecting metastasis." (PMID 32281273, 2020). "We found that STAT3 and HP1α partially colocalize in the nucleus and might physically interact, and that uSTAT3 promotes heterochromatin formation and suppresses lung cancer cell proliferation in vitro and in vivo." (PMID 32087696, 2020).